LEPR (leptin receptor)
Diseases named in the same sentence as LEPR in open-access papers (continued):
Sharing a sentence is not in itself a finding about the gene and the disease.
Obesity (continued). "Since leptin has been reported to contribute to T cell impairment in obesity, we tested if leptin receptor signaling in T cells was required for ATT dysfunction." (PMID 33724954, 2021). "In this scenario, the aberrant expression of LEPR also has a crucial role in the onset of both rare and common forms of obesity." (PMID 34208585, 2021). "Among eleven LEPR wt/- children, three showed normal weight and six obesity (double reporting cannot be excluded in the cases with obesity)." (PMID 34448070, 2021). "NPY neuron-specific LepR knockout mice develop obesity and diabetes, which is similar to that of db/db (LepR deficient mice) mice." (PMID 34307371, 2021). "We demonstrated that LepR neuron-specific deletion of Sh2b1, or adult-onset deletion of Sh2b1 in the hypothalamus (containing LepR neurons), resulted in severe obesity, insulin resistance, and liver steatosis." (PMID 32251290, 2020). "The present study identified that the LEPR rs8179183 GG genotype has an aggravating effect on several health-related variables in Korean females with obesity, particularly those with an unhealthy metabolic health status." (PMID 32517169, 2020). "Compared to the normal tissues, the expression level of each of the three obesity-related genes (LEPR, NEGR1, and POMC) in cancer tissues was found to be insignificant." (PMID 33299884, 2020). "Patients with mutation in the human leptin receptor gene (LEPR) who display extreme obesity have also been identified." (PMID 33233816, 2020). "Leptin resistance has also been observed in cases of obesity, due to reduced sensitivity of LepR to leptin, resulting in an impaired modulation of satiety." (PMID 33218163, 2020). "This review is focused on leptin and LEPR signaling in the (dys-)regulation of the cardiovascular system in the context of obesity and metabolic syndrome." (PMID 32655492, 2020). "Higher leptin concentrations and decreased sensitivity to leptin can normally be found in people with obesity, and this hormone acts through the LEPR, the I-type cytokine receptor." (PMID 32517169, 2020). "Jak2 activation has been shown to be the primary pathway by which the LepR functions on the neuroendocrine system and STAT3 signaling has been implicated in promoting obesity-mediated cancer progression." (PMID 33019728, 2020). "Mice with either LepR neuron-specific or adult-onset, hypothalamus-specific ablation of Sh2b1 develop obesity, insulin resistance, and liver steatosis." (PMID 32251290, 2020). "LEP downregulation of LEPR expression was suggested as one of the LEP resistant mechanisms for maintaining obesity." (PMID 33316917, 2020). "Due to the defection of leptin receptor-gene, they show characteristics such as obesity, hyperglycemia, insulin disorders and dyslipidemia in the case of special diet induction, which closely match the pathological characteristics of T2DM patients." (PMID 32817751, 2020). "Our results unravel an unrecognized LepR neuron Sh2b1/SNS/BAT/thermogenesis axis that combats obesity and metabolic disease." (PMID 32251290, 2020). "The leptin-receptor mutant db/db mouse develops a number of metabolic abnormalities, including obesity, altered lipid profile, and diabetes, all of which are exacerbated by a high-fat diet." (PMID 33396512, 2020). "The upregulation of LEPR and LEP and associated SOC3 in response to SARS-CoV-2 infection was in line with mechanisms that are dysregulated in the state of obesity." (PMID 33071815, 2020). "Mice that lack functional leptin or LepR (ob/ob, db/db) are hyperphagic and display severe obesity with hyperglycemia and insulin resistance." (PMID 32731387, 2020). "Obesity-related genes impact hormones and associated peptide production, including LEP, IGF2, and IGF1, and receptors, such as IGF1R, AR, FSHR, ESR1, and LEPR." (PMID 33113859, 2020). "In patients with obesity, while the leptin levels are increased, leptin receptor (LEPR) signaling is attenuated." (PMID 33105727, 2020).
Obesity (continued). "This seemingly counterintuitive observation is partially supported by data suggesting complex associations of obesity/adiposity, LEP/LEPR’s activation of various signaling pathways, and breast cancer progression, which is further complicated by ER expression." (PMID 32046756, 2020). "We herein identify LepR neurons as key Sh2b1 targets that mediate Sh2b1 protection against obesity, type 2 diabetes, and NAFLD." (PMID 32251290, 2020). "Literature data suggest that possible differences in LEP and LEPR expression in peripheral tissues, as well as species differences in obesity condition, should be taken into consideration." (PMID 33316917, 2020). "Similar to our outbred genetically normal nonobese T2D rat model, other diabetic rodent models (spontaneous, abnormal leptin/leptin receptor signaling, diet‐induced obesity) also showed a similar trend in the three‐point bending test." (PMID 33103024, 2020). "Severe insulin resistance can occur in the setting of severe obesity syndromes resulting from pathogenic variants in MC4R, POMC, LEP, and LEPR." (PMID 33210059, 2020). "In conclusion, we unravel an unrecognized LepR neuron Sh2b1/SNS/adipose energy expenditure axis that combats against obesity, type 2 diabetes, and NAFLD." (PMID 32251290, 2020). "In human and animal studies, subjects with obesity showed a lower leptin receptor mRNA level in adipose depots than lean subjects." (PMID 32316577, 2020). "Mutations in the leptin/melanocortin pathway (OB, LEPR, POMC, PCK1, MC4R) are associated with obesity in rodents and humans." (PMID 31500090, 2019). "Since leptin resistance is implicated in the pathogenesis of obesity, we herein report the effects of laparoscopic sleeve gastrectomy (LSG) on the serum levels of leptin and leptin receptor, in addition to its overall effect on leptin resistance." (PMID 31557979, 2019). "The downregulation of the leptin receptor, as a kind of leptin self-regulation, was observed in the hypothalamus of rats with diet-induced obesity." (PMID 31780867, 2019). "The brain mass was also determined in mice that recovered LepR expression before the onset of obesity." (PMID 30694175, 2019). "Socs3, a negative regulator of leptin receptor signaling, can inhibit fatty acid oxidation and mediate leptin resistance and diet-induced obesity." (PMID 31333621, 2019). "Leptin is closely correlated with obesity, which forms a sense of satiety in the brain and reserves energy in peripheral tissues via leptin receptor (LepR)." (PMID 30800100, 2019). "Leptin gene overexpression in adipocyte and elevation of circulating leptin levels can also contribute to enhanced basal lipolysis in obesity due to its action on the leptin receptor." (PMID 31284400, 2019). "As seen in adult animals, LepR reactivation before the onset of obesity led to suppressed energy expenditure in the dark phase and over a 24 hr period." (PMID 30694175, 2019). "We only evaluated the testicle weight in mice that had the LepR reactivation before the onset of obesity." (PMID 30694175, 2019). "The rodent models of obesity used in this study had defective leptin or leptin receptor (LepR) genes, and thus demonstrated persistently elevated hypothalamic eCBs." (PMID 31156558, 2019). "In contrast, LepR reactivation before the onset of obesity possibly prevented major pancreatic islet changes." (PMID 30694175, 2019). "In contrast to the results observed after LepR reactivation in adult mice, LepR reactivation before the onset of obesity completely normalized the glucose tolerance and insulin sensitivity in both male and female Ubi-LepRNull mice." (PMID 30694175, 2019). "These mice lack a functional leptin receptor, conferring impaired satiety signaling, resulting in T2D with hyperphagia, obesity, hyperglycemia, and dyslipidemia." (PMID 30696927, 2019). "Due to the dysfunction of the leptin receptor, db/db mice spontaneously develop hyperphagia-induced obesity, insulin resistance, and T2DM." (PMID 31781248, 2019).
Obesity (continued). "Recently, an increased tumor incidence and aggressiveness along with elevated leptin/leptin receptor expression and signaling activation were found in mammary tissues of rat model of breast cancer driven by western diet-induced obesity." (PMID 30634494, 2019). "We identified six different novel variants within five obesity-related genes (SIM1, POMC, PCSK1, MC4R and LEPR) in seven out of 105 children with early-onset severe obesity in a Turkish population." (PMID 30991789, 2019). "Only in rare cases can monogenic etiologies of obesity be identified, such as mutations in genes encoding select hormones (LEP, POMC) or their receptors (LEPR, MC4R)." (PMID 30185666, 2018). "In contrast, eicosanoids derived from omega-3 fatty acids exert a protective function against obesity-induced insulin resistance and NAFLD, as demonstrated by nutritional supplementation of omega-3 fatty acids in leptin receptor-deficient db/db mice." (PMID 30360467, 2018). "Hypothalamus-specific deletion of LepR induces the same degree of obesity as db/db mice, which globally lack LepR function." (PMID 30185666, 2018). "As expected, rats with leptin receptor deficiency have increased expression of Npy and decreased expression of Pomc in the ARC, supporting their causal roles in hyperphagia and obesity." (PMID 29896090, 2018). "Single nucleotide variants (SNVs) in the leptin receptor gene (LEPR) and other genes in the leptin-melanocortin hypothalamic pathway (LEP, POMC-ADCY3, PCSK1, MC4R, BDNF) have been reported in humans with obesity-related traits, and in children specifically." (PMID 30126176, 2018). "Most notably, human obesity has been associated with mutations in leptin (LEP), leptin receptor (LEPR), prohormone convertase 1 (PC1), proopiomelanocortin (POMC) and melanocortin-4 receptor (MC4R)." (PMID 30068297, 2018). "Despite advances in this field, studies dealing with this topic in human populations are still rare, and further studies are required to accurately define the role of the LEPR gene in the development of overweight and obesity." (PMID 30126176, 2018). "LEP G2548A has been associated with obesity and serum leptin levels in Turkish subjects and a study that reports a synergistic effect of LEP and LEPR polymorphisms on BMI, in a Han Chinese population." (PMID 30121879, 2018). "This is in agreement with elevated hypothalamic pSTAT3 in obesity and the fact that LEPR antagonism increases food intake and body-weight equally in lean and DIO mice – despite differences in exogenous leptin sensitivity." (PMID 29748097, 2018). "Rare human cases where leptin, or the leptin receptor, is entirely ablated have subsequently been reported and uniformly exhibit severe obesity." (PMID 30121879, 2018). "Four-week-old male leptin receptor-knockout db/db mice were used as controls for a model of obesity retaining low testosterone." (PMID 29895265, 2018). "Obesity is characterized by an increase in circulating leptin and a decrease in leptin receptor expression, leading to leptin resistance and disrupted leptin signaling." (PMID 30405455, 2018). "The effect of d-allulose on glycemia was also examined in type 2 diabetic db/db mice with genetic inactivation of the leptin receptor, which exhibits obesity and insulin resistance." (PMID 29317623, 2018). "Deletion of the LepR signaling molecule, signal transducer and activator of transcription-3 (Stat3), in POMC neurons causes mild obesity in female mice and reduces Pomc gene expression." (PMID 30304668, 2018). "We do know that obesity and exercise both influence the balance of pro-inflammatory and anti-inflammatory cytokines including leptin, and that distinct leptin receptor isoforms have been described in human skeletal muscle and adipose tissue." (PMID 29949600, 2018). "The Zucker fa/fa rat develops obesity due to a defect in the leptin receptor and presents visible obesity already at four weeks of age." (PMID 29724010, 2018).
Obesity (continued). "LEPR activity on astrocytes has been proposed to actively regulate leptin transport across the blood brain barrier, a finding consistent with evidence that central regulatory changes of LepR during obesity and inflammation often occur in astrocytes." (PMID 30231941, 2018). "In line with this fact, inactivation of leptin receptor or dephosphorylation of STAT3 in POMC neurons reduces energy expenditure and increased food intake, thereby causing obesity in db/db mice." (PMID 29979770, 2018). "Leptin exerts its roles through the leptin receptor; therefore, the leptin receptor gene is considered a biological pathway related to obesity development." (PMID 30338250, 2018). "We have assessed a role for physical exercise in preventing obesity in ZF and SHROB rats with leptin receptor deficiency." (PMID 29896090, 2018). "Due to the dysfunction of leptin receptor, the db/db mice develop hyperphagia-induced obesity, type 2 diabetes, and non-alcoholic fatty liver (NAFL) spontaneously." (PMID 30135656, 2018). "Obesity caused by damaging mutations in LEP and LEPR display an autosomal recessive mode of inheritance while obesity caused by MC4R mutations exhibit variable penetrance (recessive or co-dominant)." (PMID 30442103, 2018). "The aim of the current study was to examine the prevalence of damaging LEP, LEPR, and MC4R mutations in Pakistani families having a recessive heritance of early-onset obesity." (PMID 30442103, 2018). "In this study, we used a model of obesity and severe T2DM, the leptin receptor-deficient db/db mouse to assess alterations in bone quality and hindlimb blood flow and to examine the beneficial effects of 4 weeks administration of Exenatide." (PMID 29209277, 2017). "Previous studies have reported that individuals with the LEPR Arg109Arg genotype have lower risks of hypertension, obesity, dyslipidemia, and diabetes, which are all important established risk factors of CVD." (PMID 28368354, 2017). "In this study, we found significant differences in the copy numbers among children with obesity compared to those in normal weight children for LEPR, NEGR1 ARHGEF4, CPXCR1, and INS and four intergenic regions previously associated with obese children." (PMID 28428959, 2017). "Genetic association studies have provided insights into the genetics of early-onset obesity, identifying strongly associated genes with large phenotypic effects such as the leptin (LEP) or leptin receptor (LEPR) genes." (PMID 28771179, 2017). "Therefore, the association found in this study between rs11804091 and obesity in females may be related to a lower expression of LEPR, which could derive in insulin resistance through mechanisms such as those explained above; however, expression analyses should be performed to confirm this." (PMID 28771179, 2017). "The successful identification of several obesity genes, including leptin, the leptin receptor, tubby, and agouti, suggested this strategy would be useful even when effect sizes differ by genetic context." (PMID 29194435, 2017). "Two separate studies have shown that the reintroduction of the leptin receptors in the hypothalamus of LEPR null mice reduces obesity in different degrees and through different actions." (PMID 28771179, 2017). "The purpose of this study was to evaluate the association between CNVs in specific regions of LEPR, NEGR1, ARHGEF4, CPXCR1, and INS and in four intergenic regions (1p36.33b, 12q15c, 15q21.1a, and 22q11.21d) and obesity in Mexican children." (PMID 28428959, 2017). "The mutated genes, related to obesity, include leptin (LEP), leptin receptor (LEPR), pro-opiomelanocortin (POMC) and melanocortin-4 receptor (MC4R)." (PMID 27894098, 2017). "It is worth mentioning that only a small percentage of obesity cases are caused by mutations in single genes, such as leptin (LEP), leptin receptor (LEPR), and melanocortin 4 receptor (MC4R)." (PMID 28810876, 2017).
Obesity (continued). "The most severe form of obesity in mice and humans results from a deficiency in the genes encoding leptin (LEP) or the leptin-receptor (LEPR)." (PMID 28592656, 2017). "Bi-allelic SNVs of leptin (LEP), leptin receptor (LEPR), and pro-opiomelanocortin (POMC) are also associated with hyperphagic obesity." (PMID 28859103, 2017). "As leptin imposes an overall inhibitory action on VTA LepR neurons, resistance to diet-induced obesity by VMAT2 deletion is in line with a general role of leptin-inhibited neurons such as AgRP neurons." (PMID 28560316, 2017). "As is well known, leptin plays an important role in the relationship of LEP G2548A and LEPR Q223R with obesity, diabetes mellitus, dyslipidemia and CK." (PMID 29296187, 2017). "The purpose of this study was to investigate the effects of hypoxic living and exercise training on obesity and adipose tissue leptin/leptin receptor in dietary-induced obese rats." (PMID 27932989, 2016). "The aim of the current study is to investigate the involvement of leptin receptor signaling in the development of atrophic gastritis during diet-induced obesity." (PMID 26839577, 2016). "Others have used genetic (leptin or leptin receptor defective) and dietary models to show that obesity enhances DEN-induced hepatocarcinogenesis." (PMID 30873458, 2016). "In addition to diet-induced obesity, we also investigated whether in situ proliferation of macrophages is involved in ATM accumulation in one model of the genetically inherited obesity, the leptin receptor-deficient mice (Leprdb/db mice, commonly referred to as db/db mice)." (PMID 27031964, 2016). "The shared phenotypes of aripiprazole and mice with impaired LEP/LEPR function like “obesity”, “insulin resistance” and “glucose tolerance impaired” point to alterations of leptinergic signalling by the antipsychotic aripiprazole." (PMID 27673331, 2016). "In DIO mice, hepatic leptin receptor expression and enhanced plasma leptin concentration are reduced, suggesting that obesity induces hepatic insensitivity to leptin." (PMID 27977712, 2016). "We observed that obesity is more frequent in children with LEPR 223 AG+GG and LEPR 1019 GA+AA genotypes." (PMID 27015185, 2016). "Given the higher frequency of gastritis in obese patients, our results substantiate the role of leptin receptor signaling in obesity-induced atrophic gastritis." (PMID 26839577, 2016). "In contrast to genetic leptin or leptin receptor loss-of-function, which are extremely rare, heterozygous mutations in the melanocortin-4-receptor (MC4R) are the most common monogenic cause of obesity, accounting for around 6% of severe, early-onset obesity." (PMID 27899914, 2016). "Leptin, serving as an anti-obesity hormone by binding to leptin receptor, is secreted by mature adipocytes in proportion with the size of fat depots." (PMID 27708685, 2016). "The pharmacogenetic association of LEPR and LEP to obesity caused by antipsychotics additionally confirms this." (PMID 27673331, 2016). "Leptin plays a key role in the pathogenesis of obesity and depression via the long form of leptin receptor (LepRb)." (PMID 27739518, 2016). "Serum leptin levels correlates with obesity and hepatic steatosis and the leptin receptor in liver regulates lipid droplet accumulation in the liver." (PMID 27902747, 2016). "One of the mechanisms involved in obesity is associated with mutations in leptin signaling pathway; mutations in leptin (LEP) and leptin receptor (LEPR) gene are associated with obesity in rodents and humans." (PMID 28051281, 2016). "We then attempted to push the limits of beta cell expansion by placing LepR-KO mice on an HFD to maximise obesity-induced recruitment of new beta cells." (PMID 27003683, 2016). "Leptin was also shown to directly activate SF1 neurons since selective deletion of the LEPR from these neurons induced obesity." (PMID 26578907, 2015).